INS (insulin)
Diseases named in the same sentence as INS in open-access papers (continued):
Sharing a sentence is not in itself a finding about the gene and the disease.
diabetes (continued). "Insulin-treated diabetes, CKD and independency for ADL were independently associated with unexpected death." (PMID 33670462, 2021). "Mg-deprivation in sheep caused an impairment of insulin-mediated glucose uptake, while Mg supplementation delayed the development of the disease in a rat model of diabetes." (PMID 33573164, 2021). "Type 2 diabetes mellitus (T2DM) is the most common type of diabetes and is characterized by high blood glucose levels caused by the inability of the body’s cells to fully respond to insulin." (PMID 33816351, 2021). "In both models, high level of non-HDL cholesterol was associated with scleroedema, and in the second model, insulin use was also associated with the development of scleroedema in patients with diabetes mellitus." (PMID 33952255, 2021). "Insulin therapy should be preferred to other non-insulin treatments, as suggested by the American Diabetes Association." (PMID 33916210, 2021). "Apart from the HLA complex, which remains by far the strongest predictor of type 1 diabetes mellitus, the most important loci conferring susceptibility are located in the INS, PTPN22, IL2RA, SH2B3 genes." (PMID 34556755, 2021). "At present, it is believed that the causes of hypoglycemia in patients with diabetes mellitus are related to the use of drugs, however, for patients with non‐insulin treatment, the risk factors of hypoglycemia are mostly related to diet and exercise." (PMID 34925792, 2021). "One of the important causes of diabetes is the islet damage in the pancreas, which leads to the disorder of insulin secretion and thus causing diabetes." (PMID 34026064, 2021). "Diabetes is characterized by the destruction of glucose homeostasis and the deficiency of insulin effect on the liver, muscle, pancreas, and fat." (PMID 33937267, 2021). "Dysregulated expression of miR-7 has been proved with the loss of insulin secretion and insulin exocytosis, resulting in diabetes." (PMID 34853728, 2021). "Given this background, we conducted a systematic review of RCTs investigating the effect of oral Mg supplementation on glucose and insulin-sensitivity parameters in participants with diabetes or at high risk of diabetes compared with a placebo." (PMID 34836329, 2021). "Although close matching was achieved, some baseline cardiovascular risk factors, such as hypertension, hyperlipidemia, and insulin‐requiring diabetes mellitus, continued to differ between groups." (PMID 34056919, 2021). "Diabetes mellitus is a group of endocrine diseases associated with impaired glucose uptake that develops due to insufficiency of the hormone insulin, which is accompanied by hyperglycemia." (PMID 34639150, 2021). "The risk allele of rs7903146 interferes with HMGB1 binding, leading to reduced TCF7L2 expression and, therefore, impaired insulin secretion and increased diabetes risk." (PMID 33919522, 2021). "Histone deacetylase (HDAC) inhibitors such as butyrate have been reported to reduce diabetes risk and protect insulin-secreting pancreatic β cells in animal models." (PMID 34948127, 2021). "At present, the most direct and effective way to treat diabetes is to supplement deficient insulin creation with exogenous insulin." (PMID 34176494, 2021). "This princeps study shows that individuals with an already deficient insulin secretion capacity are more susceptible to develop steroid-induced diabetes." (PMID 33435513, 2021). "Type 2 diabetes mellitus (T2DM) is characterized by hyperglycemia that is predominantly caused by insulin resistance or impaired insulin secretion, along with disturbances in carbohydrate, fat and protein metabolism." (PMID 34207217, 2021). "Deletion of OGT in β-cells causes glucose intolerance and overt diabetes at 6 weeks of age due to a significant loss of β-cell mass and insulin secretion dysfunction in vivo." (PMID 33460647, 2021).
diabetes (continued). "In our study, insulin and metformin had different associations with clinical outcomes: around 60% of patients with pre-existing diabetes were taking metformin, and the treatment was associated with a better clinical outcome." (PMID 34439986, 2021). "In adipose tissue, PPARγ expression is downregulated by fasting and insulin-deficient diabetes but induced by exposure to a high-fat diet and insulin." (PMID 34445679, 2021). "Glycemic control through insulin replacement therapies can reduce diabetes-associated vascular complications, but even intensive glycemic control does not normalize the risk of developing these comorbidities." (PMID 33800470, 2021). "Type 2 diabetes, the most common type of diabetes, is caused by the unresponsiveness of insulin (insulin resistance)." (PMID 34571734, 2021). "Diabetes Mellitus is a chronic disorder associated with abnormally high levels of blood glucose because the body is unable to produce enough insulin to meet its needs." (PMID 33726723, 2021). "There are heterogeneous reports of atypical diabetes in LMICs, describing an entity of malnutrition-related, insulin-deficient diabetes related to pancreatic damage." (PMID 33740034, 2021). "Insulin is one of most important hormones in human body and its metabolic disarrangement in skeletal muscle is profoundly associated with the etiology of diabetes." (PMID 34063269, 2021). "For example, insulin resistance and relative insufficiency of islet cell secretion are the core causes of diabetes." (PMID 33588950, 2021). "The trial revealed improvements in glycemic control, insulin sensitivity, and dyslipidemia in individuals with or at risk for diabetes." (PMID 34371888, 2021). "Previously, it was shown that human regions syntenic to the mouse insulin secretion QTL were enriched for the human diabetes GWAS variants." (PMID 33941776, 2021). "Appropriate insulin secretion is essential for maintaining euglycemia, and impairment or loss of insulin release represents a causal event leading to diabetes." (PMID 33767668, 2021). "ER stress also induces other pathways that involve JNK, an activator of inflammation and apoptosis, and it is also implicated in the impairment of insulin signaling and development of diabetes and MAFLD progression to NASH." (PMID 34769060, 2021). "TIP-1 mice displayed a significantly reduced incidence of spontaneous diabetes, which was associated with reduced severity of insulitis and insulin autoantibody development." (PMID 33841427, 2021). "Diabetes mellitus is a complex and heterogeneous disease characterized by progressive loss of function in the insulin-secreting pancreatic β-cells." (PMID 33673206, 2021). "With diabetes being the 7th leading cause of death worldwide, overcoming issues limiting the oral administration of insulin is of global significance." (PMID 33995999, 2021). "Among those with type 1 diabetes, insulin pump use was associated with a lower likelihood of DR after adjusting for race and ethnicity, insurance status, diabetes duration, and HbA1c level (odds ratio [OR], 0.43; 95% CI, 0.20-0.93; P = .03)." (PMID 34570208, 2021). "Diabetes is a metabolic disorder caused by impaired insulin secretion or dysfunction, characterized by the elevated blood sugar levels that must be maintained at a constant level by insulin and glucagon produced by the pancreas." (PMID 34064591, 2021). "It involves daily insulin injections (or use of an insulin pump), frequent blood glucose monitoring, following a balanced diet, and regular physical activity." (PMID 38774890, 2021). "The aim of this study was to compare the effectiveness of a calorie-restricted LC diet with a Med diet on weight loss and on the main determinant of glucose homeostasis in morbidly obese, insulin-resistant individuals at high risk to develop diabetes." (PMID 33919503, 2021).
diabetes (continued). "In diabetes, beta cell deficiency, together with alpha cell insulin and somatostatin resistance, all contribute to alpha cell dysfunction and a loss of the regulation of glucagon secretion, resulting in hyperglucagonemia." (PMID 34659118, 2021). "Reports suggest that FOXO-driven protein degradation is responsible for muscle atrophy as seen during insulin-deficient diabetes." (PMID 34190986, 2021). "The two most common forms of diabetes, type I (T1D) and type II (T2D), are associated with the eventual loss of insulin-secreting pancreatic β-cells, which can occur either early (T1D) or late (T2D) in disease progression." (PMID 34149620, 2021). "According to the most widely accepted view, the major cause of impaired metabolism or diabetes in CP is defective insulin secretion." (PMID 34566890, 2021). "Moving towards the unhealthy-archetype is associated with higher levels of diabetes, obesity, and cardiovascular disease markers including insulin, glucose, LPIR, triglycerides, LDL." (PMID 34117230, 2021). "This is before considering funding more expensive long-acting insulin analogues given the morbidity and mortality associated with diabetes." (PMID 34249838, 2021). "Insulin maintains normal blood glucose levels; however, the steroid hormones counteract insulin function and increase blood glucose levels, even cause diabetes." (PMID 33484713, 2021). "Insulin dosage, female sex, BMI, HbA1c, and diabetes duration were significantly associated with increased BP." (PMID 34638531, 2021). "The Finnish Diabetes Prevention Study with impaired glucose tolerance risk population showed that the change in UA was significantly related to the change in fasting insulin." (PMID 33931084, 2021). "The authors proposed that poor metabolic regulation in insulin monotherapy was responsible for the prevalence of cancer and this is associated with the duration of diabetes." (PMID 34535145, 2021). "Insulin therapy was in general related to an increased risk of pneumonia in individuals with type 2 diabetes mellitus." (PMID 34683125, 2021). "Genetic variants that affect insulin signaling play an important role in insulin resistance (IR) in type 2 diabetes mellitus (T2DM)." (PMID 35221617, 2021). "High concentrations of FFA can inhibit insulin signaling pathways in skeletal muscle and liver, induce insulin resistance, and increase the risk of diabetes and cardiovascular diseases." (PMID 33679891, 2021). "Diabetes mellitus (DM) is a metabolic disorder characterized by persistent hyperglycemia and is caused by insulin resistance, defective insulin secretion, or both genetic and environmental factors." (PMID 33718629, 2021). "Decreased OC concentration would then impair insulin secretion and glucose tolerance, resulting in worse glycemic control and increased risk of diabetes." (PMID 33833796, 2021). "This unbiased analysis identified enrichment of pathways related to insulin signaling and T2D predisposition in multiple organs, thereby predicting a correlation between Mof levels and diabetes predisposition on the gene regulatory level." (PMID 34707105, 2021). "Gestational Diabetes is the onset of diabetes during pregnancy due to increased adiposity and hormonal variations caused by the placenta, resulting in insulin resistance." (PMID 34940233, 2021). "Glucagon-like peptide-1 receptor (GLP-1R) agonists are promising agents for treating type 2 diabetes mellitus, since they augment glucose-dependent insulin secretion with minimized low risk of hypoglycaemia." (PMID 33995091, 2021). "GH is an antagonist hormone to insulin, which increases lipolysis and gluconeogenesis and predisposes to insulin resistance, which is the main factor in diabetes origin." (PMID 33796075, 2021). "Herein, we identified a novel nonsense INS mutation causing an early termination at the 46th residue of PPI (PPI-R46X) in two unrelated patients with early-onset diabetes." (PMID 35069438, 2021).
diabetes (continued). "An absolute or progressive loss of adequate insulin secretion and insulin resistance, leads to the cardinal manifestation of diabetes which is hyperglycemia." (PMID 33708143, 2021). "MODY-causing INS mutations have been associated with early onset diabetes as well as ketoacidosis in some cases, whereas rare cases with BLK mutations have also been associated with overweight." (PMID 34079523, 2021). "During the follow-up, the event rate increased with the use of diuretics and insulin compared with the antidiabetic monotherapy probably from an association with the severity of heart disease and diabetes, respectively." (PMID 34823531, 2021). "In another report, the use of the matrix patch of pectin-insulin was shown to offer protection against the devastating cardiovascular effects associated with the conventional treatment of diabetes." (PMID 33466845, 2021). "Risk factors such as obesity, advanced age, and family history of diabetes can lead to pancreatic β cell dysfunction, resulting in insufficient insulin production to overcome the insulin resistance associated with pregnancy." (PMID 34022907, 2021). "These metabolic responses are also involved in the pathophysiology of other diseases, such as diabetes and prediabetes, leading to chronic inflammation and consequent endothelial damage can cause insulin resistance and impaired insulin secretion." (PMID 33546150, 2021). "Diabetes mellitus (DM) is a chronic metabolic disorder caused by a failure in insulin production or a decrease in insulin sensitivity and function, affecting the lipid and carbohydrate metabolism." (PMID 34040519, 2021). "Diabetes is caused by the absence or insufficient production of insulin, or an inability to use insulin." (PMID 33946468, 2021). "Active hormone therapy, indeed, represents a significant risk factor of diabetes among breast cancer survivors, particularly aromatase inhibitors, which exert a powerful detrimental effect on insulin sensitivity and central adiposity." (PMID 34066685, 2021). "For example, the recommendations of the Dutch Diabetes Association about insulin biosimilars are in line with current scientific evidence and do therefore not correspond to those from IDF Europe." (PMID 33557030, 2021). "Diabetes mellitus (DM) is a metabolic syndrome characterized by a high glucose level caused by decreased insulin level or insulin insensitivity." (PMID 33889601, 2021). "Endoplasmic reticulum stress, mitochondrial dysfunction, and cholesterol metabolism are thought to cause type 2 diabetes mellitus via activation of inflammatory pathways thereby inhibiting insulin secretion." (PMID 34692675, 2021). "In support, we observed better processing speed associated with metformin use among diabetes patients who were using oral hypoglycemic agents or insulin." (PMID 34966358, 2021). "Type 1 diabetes mellitus is a chronic autoimmune disease caused by the immune-mediated destruction of insulin-producing β-cells in pancreatic islets, leading to insulin deficiency." (PMID 34301918, 2021). "In the present study, a telemedicine offer with diabetologists from the nursing home’s point of view does not fit their needs because treating physicians are comfortable with managing non-insulin-required diabetes." (PMID 34769665, 2021). "Diabetes, especially treated with insulin, is a well-established risk factor of Absorb device thrombosis." (PMID 34300332, 2021). "ED is also linked to insulin resistant states including obesity, diabetes, and the metabolic dysfunction." (PMID 34646376, 2021). "SIRT1 has been linked with insulin sensitivity and glucose homeostasis and studies have shown that patients with diabetes had an 80% reduction in SIRT1 levels." (PMID 34639171, 2021). "Type 2 diabetes mellitus is mainly caused by two physiological and pathological defects, i.e. insufficient insulin secretion together with insulin resistance." (PMID 33995091, 2021).
diabetes (continued). "In patients with diabetes, ketoacidosis is caused by an acute decrease in insulin secretion and action in a severe insulin resistant state." (PMID 34188679, 2021). "Heterozygous mutations in the genes encoding the transcription factors hepatic nuclear factor-4α and -1α (HNF4A and HNF1A, respectively) result in reduced insulin secretion and mutation carriers develop diabetes in childhood or early adulthood." (PMID 33569631, 2021). "In these populations, PFAS was found to be associated with an increased risk of diabetes and disruption of glycemic indicators, including increased blood glucose, glycated hemoglobin (HbA1c), and insulin secretion." (PMID 34022907, 2021). "Insulin is a high risk medicine which is crucial for the management of diabetes in millions of patients worldwide." (PMID 33807829, 2021). "Despite strict adherence to insulin therapy, the majority of diabetic patients have inadequate control of glycemia and suffer from diabetes-associated complications." (PMID 34452266, 2021). "Conversely, type 2 diabetes mellitus is associated with a profound metabolic dysregulation, resulting from impaired insulin secretion, insulin resistance, or a combination of both." (PMID 34831029, 2021). "Diabetes mellitus (DM) is a chronic, multifactorial set of metabolic diseases arising from deficiencies in insulin synthesis, insulin potency, or both which often manifests as severe hyperglycaemia." (PMID 34194523, 2021). "Type 1 diabetes mellitus (T1D) is a chronic autoimmune disease that causes absolute deficiency in insulin production." (PMID 34283902, 2021). "Type 1 diabetes mellitus is a chronic autoimmune disease characterized by a severe deficiency of insulin secretion due to pancreatic β-cells loss." (PMID 34831029, 2021). "Diabetes mellitus (DM) is a group of chronic metabolic disorders that are characterized by hyperglycemia, defective insulin secretion and/or insulin action and strong correlation with higher risk of disease-related complications." (PMID 34209369, 2021). "Systemic, intravitreal, and subconjunctival administration of insulin restores prosurvival IR and Akt kinase activities and reduces retinal cell death associated with diabetes." (PMID 33915127, 2021). "Graeme Bell reported in 2007 that mutations in the insulin gene that cause abnormalities in insulin maturation and folding cause diabetes." (PMID 34717951, 2021). "Diabetes, metabolic disorder caused by insufficient insulin secretion or insulin utilization disorder." (PMID 34366917, 2021). "The novel MDH cluster represents a group of people with mild diabetes and very low risk of glycaemic deterioration towards insulin requirement." (PMID 34110439, 2021). "Diabetes mellitus (DM) is characterized by elevated glucose levels caused by either a defect in insulin secretion from the pancreas or peripheral resistance to insulin effects." (PMID 34650878, 2021). "In the current study, insulin treatment was associated with increased mortality and incidence of severe/critical complications in patients with COVID-19 and diabetes." (PMID 34367067, 2021). "Recently, miRNAs were featured efficiently in association with insulin production, residual β-cell function, and disease complications of diabetes." (PMID 34917685, 2021). "The study not only expends the list of INS mutations associated with diabetes, but also provides genetic and biological evidence underlying the regulation mechanism of PPI translocation." (PMID 35069438, 2021). "Diabetes is a metabolic syndrome associated with hyperglycemia, β‐cell dysfunction, impaired secretion of insulin, or developing insulin resistance." (PMID 33598184, 2021). "Misfolded proinsulin in the ER lumen triggers the UPR to enhance protein folding and degradation but in case of INS mutations (causing mutant INS-gene-induced diabetes of youth, MIDY), the misfolding continues, resulting in persistent activation of the UPR." (PMID 33967960, 2021).